UCP1 (uncoupling protein 1)
Diseases named in the same sentence as UCP1 in open-access papers (continued):
Sharing a sentence is not in itself a finding about the gene and the disease.
Obesity (continued). "In genetically obese ob/ob mice and mice with diet-induced obesity, high concentrations of inflammatory markers (like e.g., tumor necrosis factor α or IL-1β) inhibit activation of PPARγ, leading to the decreased expression of UCP1, that translates to impaired cold-induced thermogenesis." (PMID 32872317, 2020). "Together, these findings demonstrate the effects of sesamol in inducing Ucp1 and in increasing energy expenditure, further highlighting the use of the Nrf2 activation in stimulating thermogenic adipocytes and in increasing energy expenditure in obesity and its related metabolic diseases." (PMID 32443555, 2020). "detected three other point mutations in the coding region of the Ucp1 gene: Arg40Trp (rs573078239) in exon 1 and Lys257Arg (rs1431343082) and Met229Leu (rs2270565) in exon 5, but none of them showed an association with the development of obesity." (PMID 32450815, 2020). "Furthermore, the upregulated expression of UCP-1 in adipose tissue could boost heat production, which had positive effects on alleviating obesity." (PMID 32218367, 2020). "Therefore, this study was performed to evaluate the preventive and curative effects of CM resin alcoholic extract against HFD induced obesity and dyslipidemia with the respect to its impact on the expression of obesity development related cytokines, leptin, adiponectin and UCP1 in rats." (PMID 32197395, 2020). "BAT, including classical BAT and the newly identified beige adipose tissue, functions to resist cold and obesity through adaptive heat generation, namely, thermogenesis, in processes mainly mediated by the expression and activation of mitochondrial uncoupling protein 1 (UCP1)." (PMID 31817377, 2019). "Finally, HFD feeding may interfere with CL’s effectiveness to activate UCP1, which may be an important consideration for utilizing β3 adrenergic agonists as a therapeutic for obesity." (PMID 30804793, 2019). "However, concerns may be raised that this outcome of UCP1 ablation is restricted to this very special inbred and particularly obesity-prone mouse strain." (PMID 30807213, 2019). "The present study demonstrated that rats fed diets containing bilberry counteracted pre-obesity events including increased liver index, hepatic steatosis, cecal microbiota dysbiosis, enhanced serum total cholesterol levels, whereas iBAT distribution was stimulated and Ucp-1 was upregulated." (PMID 31208043, 2019). "That the metabolic effects of UCP1 are discernable even in these mice where the BAT is rather involuted (since the mice were kept at thermoneutrality) is of translational importance, as it implies that even minor amounts of UCP1 may affect metabolism and thus also obesity development in humans." (PMID 30807213, 2019). "To test if H. polygyrus-induced M2 cells may promote adipose tissue browning, and contribute to increased resistance to dietary obesity, we examined the UCP1 expression and mitochondrial level in the recipient mice that were transferred with macrophages from normal or helminth infected donors." (PMID 29545532, 2018). "Increasing UCP1 expression in BAT could be considered as a useful anti-obesity treatment option." (PMID 29329235, 2018). "The anti-obesity action of chronic NP-1 administration might be mediated by TNFα, which is known to have anorectic actions in the hypothalamus and to regulate both Dmnt1 and Ucp1 expression in adipose tissues." (PMID 29959379, 2018). "Moreover, UCP-1 overexpression in adipose tissue suppressed obesity." (PMID 28804438, 2017). "Therefore, selectively inducing mitochondrial fragmentation in BAT could be a strategy mimicking Ucp1 activation and a potential therapy for obesity, which would bypass the need for adrenergic stimulation." (PMID 28539390, 2017). "Thus, CPT1AM-mediated increase in lipolysis, UCP1 protein expression and mitochondrial activity in brown adipocytes may lead to a new treatment of obesity and related disorders." (PMID 27438137, 2016).
Obesity (continued). "However, a possibility to utilize PFOA-/PFOS-like substances for activating UCP1 therapeutically in obesity-prone humans may also be envisaged." (PMID 26041126, 2016). "Thus, with all the available evidence to date, we suggest that the therapeutic potential of UCP1-positive mitochondria in combating obesity and its metabolic complications will likely be realized in humans by the acute activation of existing BAT and/or the expansion of BAT depots." (PMID 26528238, 2015). "Earlier studies show that enhanced expression of UCP1 in WAT of mice could reduce obesity." (PMID 25587272, 2014). "Besides the UCP1-3826G/A, genetic variations supporting the relationship between past cold adaptation and the present susceptibility to obesity have not been extensively studied." (PMID 25533680, 2014). "Increased expression of UCP1 increases the proportion of energy derived from fatty acid oxidation that is released as heat, rather than being deposited as white adipose tissue; this provides an important avenue by which exercise facilitates increased energy expenditure and counteracts obesity." (PMID 20885954, 2010). "Impaired FGFR1/β-Klotho signaling, as observed in obesity, diminishes FGF21 responsiveness, whereas pharmacological activation of this pathway restores thermogenic capacity through UCP1 induction." (PMID 41596403, 2026). "Enhanced UCP1 abundance and an increase in the thermogenic capacity of the BAT have been shown to reduce obesity and improve glucose tolerance and insulin sensitivity in high-fat diet-fed mice." (PMID 40983918, 2025). "Visceral Progenitor with Mesothelial origin cells likely represent beige adipocyte progenitors with high mitochondrial activity and Uncoupling Protein 1 (UCP1) expression, potentially mitigating obesity-related metabolic dysfunction." (PMID 41303487, 2025). "Activation of thermogenic pathways, particularly via cAMP-mediated signaling that upregulates UCP1, PRD1-BF1-RIZ1 homologous domain containing 16 (PRDM16), and PGC1α, represents a promising therapeutic approach for obesity." (PMID 41374084, 2025). "Activation of mitochondrial UCP1 can enhance thermogenesis in both BAT and WAT, representing a promising therapeutic strategy for obesity." (PMID 40369420, 2025). "The upregulation of uncoupling protein-1 (UCP-1) in adipose tissue indicates enhanced energy expenditure and browning of white adipocytes, which is crucial for combating obesity." (PMID 40508058, 2025). "Activating the UCP1-dependent thermogenic pathway in BAT and iWAT can promote EE in the body and improve HFD-induced obesity." (PMID 40076847, 2025). "All these compounds activate the β3-ARs pathway and increase the expression of thermogenic markers such as UCP1, PRDM16, and PGC1α, thereby limiting obesity." (PMID 41011119, 2025). "It is of concern that AT-II also counteracts obesity and promotes energy expenditure in DIO mice, accompanied by an increase in the expression of the thermogenic gene Ucp1 in WAT." (PMID 41492457, 2025). "Epicatechin decreases the rate of weight gain via increasing the expression of PGC-1α, UCP1, and SIRT1 and 3 involved in mitochondrial energy expenditure in a rat model of HFD-induced obesity." (PMID 40642166, 2025). "Considering that fucoxanthin increased mitochondrial UCP1 expression in WAT and the weight of BAT, which is enriched in mitochondria, it is likely that fucoxanthin exerts its anti-obesity effects by acting on the mitochondria." (PMID 40220069, 2025). "UCP1 transcription mediated by the SIRT5-C/EBP beta axis is possibly crucial for the regulation of energy balance and obesity-related metabolism." (PMID 39769065, 2024). "Together, these findings emphasize that under the KD, the activation of UCP1 can modulate BAT activity, facilitated by factors, such as PPARγ and ketone esters, highlighting its capacity to address metabolic dysfunction and obesity-related complications." (PMID 39000187, 2024).
Obesity (continued). "Also, Mirabegron, a β3-AR agonist, as well as Troglitazone, may stimulate UCP1 expression and consequently browning process, although their use shows different limitation in the application for obesity, including a reduced effectiveness and the appearance of side effects." (PMID 39204091, 2024). "First, we examined how obesity affects the expression of the fibronectin type-III domain containing 5 (FNDC5) and uncoupling protein 1 (UCP1) genes in male Wistar rats." (PMID 40071055, 2024). "In the first, adipocytes have mitochondria that make the uncoupling protein 1:UCP-1, whereas the second is increased in obesity." (PMID 39857648, 2024). "On the other hand, after receiving 100 or 150 mg/kg of 7-MEGATM, the levels of PPARα and UCP-1 increased in HFD groups, suggesting that lipid metabolism had improved in HFD mice thereby ameliorating obesity." (PMID 38909257, 2024). "We believe that UCP1 in ATM can be a novel therapeutic target to treat and prevent diet-induced obesity." (PMID 39473019, 2024). "Our research presents novel findings that TRPV1 activation by CAP at thermoneutrality counters obesity in WT mice and promotes PRDM-16-dependent UCP-1 transcription." (PMID 39204203, 2024). "WAT from obese participants, serum T4 levels positively correlated with mRNA levels of UCP1, CIDEA and PRDM16 in both sWAT and vWAT from individuals with obesity." (PMID 39087083, 2024). "In this context, the findings that ABA-C-treated mice exhibit increased expression of browning markers such as UCP1 and PGC-1α underscore the potential of this supplementation to stimulate energy expenditure and combat obesity." (PMID 39796338, 2024). "Sutent, for example, was found to be capable of upregulating UCP1 in BAT and elevating calorie consumption to protect against obesity." (PMID 39062047, 2024). "In contrast, brown adipose tissue (BAT) dissipates energy through the activation of uncoupling protein 1 (UCP1) found in mitochondria and burns fat through thermogenesis to defend against obesity." (PMID 38333010, 2024). "In obesity, increased adiposity and inflammatory cytokines disrupt BAT thermogenesis by reducing the expression of UCP1, essential for heat production." (PMID 38928386, 2024). "To investigate the relationship between aging and obesity further, we analysed BAT UCP1 expression separately in younger (aged 18-39 years, n = 13) and older (aged ≥40 years, n = 40) participants." (PMID 38917410, 2024). "Hyperoside (HPF), an anti-obesity drug, stimulates AMPK and PGC-1α through a Ucp1-dependent pathway." (PMID 38672499, 2024). "In contrast, BAT, rich in mitochondria and containing uncoupling protein 1 (UCP1), is responsible for heat production that positively affects obesity and metabolic diseases." (PMID 39267855, 2024). "Consistent with our initial metabolic characterizations, knockout mice were not susceptible to diet-induced obesity or dysregulated glucose handling as hypothesized, suggesting diet-induced recruitment of UCP-1 and energy balance were unaffected by p300 or CBP knockdown." (PMID 39140972, 2024). "The upregulation of thermogenic genes such as Ucp1 and Pgc1α in the BAT of female offspring suggests enhanced BAT activity and energy expenditure, which are known to protect against obesity and glucose intolerance." (PMID 39623508, 2024). "UCP1-expressing ATM produce the heat to mediate lipolysis of adipocytes, indicating that this can be a novel strategy to treat and prevent diet-induced obesity." (PMID 39473019, 2024). "Upregulation of adiponectin and SIRT-1 expression after sleeve gastrectomy in a murine model of sequential HFD-induced obesity and streptozocin-induced T2DM resulted in browning of SAT via PPARγ, PGC-1α, and UCP1 activation." (PMID 39063184, 2024). "Our research presents novel findings that demonstrate that TRPV1 activation by CAP at thermoneutrality counters obesity in WT mice and promotes PRDM-16-dependent UCP-1 transcription." (PMID 39204203, 2024).
Obesity (continued). "This work systematically analyzed the role of TRPV1 activation in countering obesity in WT mice housed in the TNZ and delineated the mechanism of UCP1 activation in energy expenditure in the TNZ using WT and UCP-1−/− mice." (PMID 39204203, 2024). "Our study demonstrated that SL extracts have anti-obesity properties by reducing ACC1, C/EBPα, and the F/B ratio, and by inducing AMPK, UCP1, B. vulgatus, and F. prausnitzii." (PMID 36839173, 2023). "We observed resistance to diet-induced obesity in UCP1 KO mice fed HFD at ambient temperature, with significantly higher expression of UCP1-independent thermogenic markers, compared to WT mice." (PMID 37240054, 2023). "Chrysophanol administration in mice with HFD-induced obesity substantially elevates SIRT6 and UCP-1 expression within WAT." (PMID 38053837, 2023). "•Not only UCP1 augmentation but also UCP1 activation is essential for enhanced DIT and protection from obesity." (PMID 37499977, 2023). "Promoting metabolic inefficiency in skeletal muscle by UCP1 or UCP3 overexpression can increase metabolic rate and prevent diet-induced obesity." (PMID 37249575, 2023). "An adipose tissue-specific Notch signaling null model also exhibited resistance to diet-induced obesity and elevated WAT browning, UCP1 expression, energy expenditure, and insulin sensitivity." (PMID 36674862, 2023). "Additionally, CGA diminish body weight and fat deposition which may be related to peroxisome proliferator-activated receptor gamma, coactivator 1α (PGC-1α), and uncoupling Protein 1 (UCP1) in the monosodium glutamate (MSG)-induced obesity mouse model and the oleic acid-induced HepG2 cells." (PMID 37710316, 2023). "Earlier studies using a model of diet-induced obesity established that when treated subcutaneously with CL316243, rat BAT had markedly increased UCP1 content." (PMID 36671058, 2023). "Apigenin also enhances uncoupling protein-1 (UCP-1) and PGC-1α in SAT and BAT to consume plasma free fatty acids, thereby decreasing obesity-related IR." (PMID 37036026, 2023). "Collectively, these discoveries highlight the therapeutic potential of chrysophanol in combating obesity and related metabolic disorders by virtue of its ability to upregulate SIRT6, subsequently promoting the upregulation of PGC-1α and UCP-1 in BAT." (PMID 38053837, 2023). "Glucocorticoid stimulation has been found to diminish thermogenic capacity with a decreased uncoupling protein 1 (UCP1) protein level and an increased accumulation of lipids in BAT, which has thus been considered to mediate glucocorticoid-induced obesity." (PMID 37435495, 2023). "We showed that deletion of GADD45A significantly increases Ucp1 expression and induces iWAT browning, protects mice from HFD-induced obesity, and improves glucose tolerance and insulin sensitivity." (PMID 37807064, 2023). "We observed similar results such that both when UCP1 KO mice, in this case on an FVB/N background, were fed a chow diet (not shown here) or a high-fat cafeteria diet, the KO mice were protected against obesity, as was also observed on a C57Bl/6 background." (PMID 37661736, 2023). "We have previously shown that eicosapentaenoic acid (EPA) ameliorated high-fat diet (HFD)-induced obesity by activating brown fat in C57BL/6J (B6) mice at thermoneutrality (30 °C), independently of UCP1." (PMID 37240054, 2023). "In our model of obesity induced by litter size reduction, we observed BAT dysfunction and UCP-1 gene expression reduction." (PMID 38274208, 2023). "WAT is responsible for fat storage, whereas BAT dissipates chemical energy as heat via high levels of uncoupling protein 1 (UCP1), thus combating hypothermia and obesity." (PMID 37291666, 2023). "Some of the well-known obesogenic or obesity marker genes, such as Hsd11b1 and Lep, were obviously upregulated by OVX, while some of the well-known fatty acid oxidation genes, e.g., Ucp1 were downregulated by OVX." (PMID 37834368, 2023).
Obesity (continued). "In an animal study, VDR knockout C57BL6 mice resulted in UCP-1 expression and protection from diet-induced obesity, which means disrupted expression of VDR results in a compensatory increase in UCP-1 expression." (PMID 36771240, 2023). "Obesity induces systemic and hepatic inflammation, and BAT recruitment and UCP1 activation by cold have been suggested to participate in resolving systemic and hepatic inflammation." (PMID 38048357, 2023). "In some studies, butyrate stimulated thermogenesis of brown adipose tissue (BAT) via the upregulation of uncoupling protein-1 (UCP1) expression, thus increasing energy expenditure and improve HFD-induced obesity." (PMID 36909336, 2023). "In this review, we highlight some of the key findings obtained from these transgenic mice, including Ucp1 KO mice and other models targeting the HIF pathway in adipocytes, macrophages, or endothelial cells, to decipher their roles in diet-induced obesity." (PMID 37907745, 2023). "Vitamin D insufficiency also downregulates the expression of UCP1 in WAT and inhibits AMPK/SIRT1 activity, leading to obesity progression in rats." (PMID 37764855, 2023). "Other researchers have demonstrated the existence of uncoupling protein 1 (UCP1)+ brown adipocytes within IMAT in mice, providing a therapeutic target for obesity by acting on energy dissipation." (PMID 37920255, 2023). "Our group has recently reported that increased non-12α-hydroxylated BAs (non-12OH BAs) lead to an obesity-resistant phenotype in mice through TGR5 mediated brown adipose tissue (BAT) activation and upregulation of uncoupling protein 1 (UCP1) expression." (PMID 35440584, 2022). "DHF supplementation also increased uncoupling protein 1 (UCP1) and AMP-activated protein kinase (AMPK) protein in BAT, consistent with protection from diet-induced obesity." (PMID 36061902, 2022). "In uncoupling protein 1 knockout (UCP1 KO) mice, however, elevated endogenous FGF21 levels mediate resistance against diet-induced obesity." (PMID 36034414, 2022). "By promoting thermogenesis (i.e., heat production) via uncoupling protein 1 (UCP1), functional BAT can increase energy expenditure and aid obesity treatment and prevention." (PMID 36438760, 2022). "Also, in accordance with the resistance to obesity of mice harboring transgenic overexpression of UCP1 in WAT and the involvement of UCP1 in diet-induced thermogenesis, it is often speculated that NST mediated by UCP1 could serve as a target for obesity treatment." (PMID 35466996, 2022). "To further determine the importance of ROS production in the promotional effect of TRPV1 knockout on obesity-related hypertension induced by UCP1 knockout, we added tempol, an ROS scavenger, to the feed of TRPV1/UCP1 double knockout mice." (PMID 35043013, 2022). "Genetic deletion of TNF receptors in obese mice led to reduced apoptosis and induced transcriptional activation of Ucp1 in BAT, suggesting a significant role of TNFα-mediated inflammatory response in thermogenic adipobiology during obesity." (PMID 35493493, 2022). "BAT thermogenesis relied on UCP1, which activity in BAT is reduced due to the development of obesity." (PMID 36386906, 2022). "It is reported that H. polygyrus infection elevates UCP1 expression, promoting the browning of WAT in mice, by which can increase energy expenditure and attenuate obesity in mice." (PMID 35281054, 2022). "Ginsenoside Rb2 can ameliorate obesity and metabolic disorders by inducing gene expression of PGC-1α and UCP1." (PMID 35647185, 2022). "Overexpression of UCP1 and UCP3 in brown adipose tissue and skeletal muscle appears to mimic endurance training and prevent the development of obesity in female mice by reducing triglyceride accumulation." (PMID 36009191, 2022). "The obesity resistance is dependent on FGF21, as UCP1/FGF21 dKO mice gain similar body weight and fat mass as WT and FGF21 KO control mice." (PMID 36034414, 2022).